SKP2 (S-phase kinase associated protein 2)
Diseases named in the same sentence as SKP2 in open-access papers (continued):
Sharing a sentence is not in itself a finding about the gene and the disease.
esophageal cancer (6 papers, 2017 to 2023). A primary or metastatic malignant neoplasm involving the esophagus. "In prostate, gastric, and esophageal cancers, higher levels of Skp2 are associated with tumor metastasis and poorer survival, while down-regulation of Skp2 leads to inhibition of tumor growth and metastasis." (PMID 30250282, 2018). "Skp2 is overexpressed in esophageal carcinoma tissues and closely related with tumor poor prognosis, and perturbation of the Skp2-Cks1 interaction by inhibitors or RNAi could inhibit the proliferation and metastasis of tumor cells." (PMID 34702937, 2021). "Pathway anaylsis showed that UBE2C mainly influenced the biological function of esophageal cancer by synergistic effects with CDK1, PTTG1 and SKP2." (PMID 34488675, 2021). "The PPI results of the first five KEGG pathway proteins showed that UBE2C mainly influenced the biological function of esophageal cancer by synergistic effects with CDK1, PTTG1, and SKP2 (all three are involved in the cell cycle pathway)." (PMID 34488675, 2021). "However, until now, no reports regarding the effects of SKP2 on the bystander response of esophageal cancer (EC) have been found." (PMID 28178195, 2017).
astrocytoma (5 papers, 2015 to 2025). "Rescue of ADAR2 editing activities in astrocytoma prevented tumor growth by modulating cell division cycle 14B (CDC14B) pre-mRNA editing and in turn influencing downstream S phase kinase-associated protein 2 (SKP2)/p21/p27 axis." (PMID 37612540, 2023). "ADAR2 promotes CDC14B editing and overexpression in astrocytoma cells, leading to Skp2 degradation and upregulation of p21 and p27 proteins, consequently causing cells to accumulate in the G1 phase of the cell cycle." (PMID 30524204, 2018). "There is an inverse correlation between p27/KIP1 and SKP2 in a series of astrocytic gliomas: SKP2 expression was absent or greatly reduced in well-differentiated astrocytomas, but increased significantly in several GBM samples." (PMID 33665742, 2021).
cardiac hypertrophy (5 papers, 2019 to 2022). "Furthermore, overexpression of the S-phase kinase-associated protein 2 (Skp2) promoted autophagy and rescued cardiac hypertrophy induced by Ang II." (PMID 33748196, 2021). "In a recent study, miR-365 was revealed to promote the progression of cardiac hypertrophy by downregulating the expression of S-phase, kinase-associated protein 2 (Skp2), an enzyme involved in the physiological and pathological processes of the heart, such as cardiomyocyte proliferation." (PMID 31547607, 2019). "Downregulation of Skp2 activates an mTOR signaling pathway, leading to the suppression of autophagy and an increase in cardiac hypertrophy." (PMID 31547607, 2019). "And, Skp2 knock-down further inhibited autophagy and cardiac hypertrophy in mice with MI." (PMID 33748196, 2021). "MiR-365 induces cardiac hypertrophy and inhibits autophagy through mediating Skp2 expression." (PMID 33240671, 2020). "Furthermore, SKP2 expression could improve post-ischemic cardiac function, and it has a therapeutic effect on pathological cardiac hypertrophy." (PMID 35865382, 2022).
head and neck squamous cell carcinoma (5 papers, 2018 to 2023). A squamous cell carcinoma that arises from any of the following anatomic sites: lip and oral cavity, nasal cavity, paranasal sinuses, pharynx, larynx, and salivary glands. "Prexasertib, an inhibitor of CHK1/2 (checkpoint kinase 1/2), reduced NOTCH signaling and Skp2, enhanced the in vitro and in vivo response of head and neck squamous cell carcinoma to cisplatin and radiation, in line with another study that claimed that Skp2 is a downstream target of NOTCH signaling." (PMID 34068643, 2021). "Excessive amount of Skp2 results in a loss of p27 and this oncogenic role of Skp2, corresponding to up-regulation of Skp2 in tumor tissues, has been observed in a wide range of human cancers, including lung, breast, colorectal, head and neck squamous cell carcinoma (HNSCC)." (PMID 30176860, 2018). "We investigated the role of Skp2 and its ubiquitin-proteasome pathway in head and neck squamous cell carcinoma (HNSCC) using a panel of cell lines with and without human papillomavirus (HPV+, HPV−)." (PMID 30333956, 2018).
liver fibrosis (5 papers, 2016 to 2023). "Other E3 ligases that are moderately increased upon CCl4-induced liver fibrosis include Rnf4 (ring finger protein 4), Skp2 (S-phase kinase-associated protein 2), Ttc3 (tetratricopeptide repeat domain 3), and Tnfaip3 (tumor necrosis factor alpha-induced protein 3)." (PMID 33261190, 2020). "Pd-MSCs-EVs ameliorated TGF-β1-induced fibrosis by deactivating HSCs in a miR-378c/SKP2-dependent manner, which may be an efficient therapeutic candidate for liver fibrosis." (PMID 37798761, 2023). "Further studies suggested that Sjp40-induced senescence could be mediated by activating SKP2/P27 signaling in LX-2 cells, which provided novel insights into the mechanisms of treatment of liver fibrosis in the future." (PMID 28325896, 2017). "In conclusion, SEA might slow down the progression of liver fibrosis by promoting HSCs senescence through the FoxO3a/SKP2/P27 pathway." (PMID 28036393, 2016). "In addition, exogenous SKP2 could rescue the fibrotic and EMT markers of HSCs repressed by miR-378c, suggesting that miR-378c might abate liver fibrosis by targeting SKP2 in HSCs." (PMID 37798761, 2023). "The results above demonstrated that miR-378c might abate liver fibrosis by targeting SKP2 in HSCs." (PMID 37798761, 2023).
lung adenocarcinoma (5 papers, 2013 to 2024). A carcinoma that arises from the lung and is characterized by the presence of malignant glandular epithelial cells. "In the lung adenocarcinoma, the expression of OCT-3/4 was increased in the A549 cells treated with 5-fluorouracil (5-FU), and decreased the expression of S phase kinase associated protein-2 (Skp2)." (PMID 32178477, 2020). "The close association of SKP2 expression with MSI and TMB was also observed in multiple neoplasms, especially for DLBC (lymphoid neoplasm diffuse large B-cell lymphoma) (ρ = −0.51, p < 0.05) in MSI, as well as KICH, LUAD (lung adenocarcinoma), and READ in TMB (ρ > 0.3, p < 0.05)." (PMID 37308972, 2023).
lymph node metastasis (5 papers, 2012 to 2023). "Moreover, for the first time, we proved the occurrence of Skp2 and Slug in the same cancer cell nuclei in tumor tissue with high Gleason score and lymph node metastasis." (PMID 33799604, 2021).
metastatic melanoma (5 papers, 2011 to 2023). A melanoma that has spread from its primary site to another anatomic site. "In addition, increased copy number at the Skp2 locus might also be associated with overexpression of Skp2 protein in human metastatic melanoma tissues." (PMID 21386910, 2011). "This Skp2 inhibitor protects p27 and p21 from ubiquitination degradation, thereby decreasing the viability of metastatic melanoma cell lines 501 Mel, SK-MEL-147, and SK-MEL-173 and inducing their apoptosis." (PMID 31038581, 2019). "An S-phase kinase-related protein 2 (Skp2) inhibitor, designated SKPin C1, has been developed and confirmed to have an inhibitory effect on metastatic melanoma cells." (PMID 31038581, 2019). "The clarification on the correlation between Skp2 expression and survival in metastatic melanoma patients awaits future study with a longer follow-up time." (PMID 21386910, 2011). "In our study, neither nuclear nor cytoplasmic Skp2 expression was associated with five-year survival in 133 cases of metastatic melanoma patients." (PMID 21386910, 2011). "Betulinic acid, a plant-derived Skp2 inhibitor, has been demonstrated to exhibit antitumor activity and low cytotoxicity in Phase 1 clinical trials (NCT00701987 and NCT030904511) against cutaneous metastatic melanoma." (PMID 37089937, 2023). "In addition, cytoplasmic Skp2 expression was not correlated with age or sex in metastatic melanoma." (PMID 21386910, 2011).
metastatic tumors (5 papers, 2008 to 2021). "Statistical analysis showed that the expression of SKP2 (Z = -1.182, P = 0.237), cyclin E (Z = -2.670, P = 0.008), and stathmin (Z = -2.487, P = 0.013) was higher in metastatic tumors than in primary high-grade OSCs." (PMID 25106448, 2014). "In addition, amplification of SKP2 at chromosome 5p13 has been reported, and tends to be observed in metastatic tumors whereas overexpression of SKP2 is reported in early cancers." (PMID 23226679, 2012). "But Skp2 expression was not significantly different between primary and metastatic tumors (P = 0.136)." (PMID 18922157, 2008).
oral squamous cell carcinoma (5 papers, 2013 to 2023). "They confirmed that downregulation of SKP2 could significantly reduce the migration and invasion ability of oral squamous cell carcinoma cells." (PMID 37308972, 2023). "Previously, the elevated expression level of SKP2 was identified in a few cancers, such as COAD and oral squamous cell carcinoma." (PMID 37308972, 2023).
sarcoma (5 papers, 2017 to 2026). A usually aggressive malignant neoplasm of the soft tissue or bone. "RB1, a gene classified as a driver in sarcoma by COSMIC, is also well connected in our solution, linking protein kinase C inhibitor staurosporine to the seed genes MYC, SKP2 and DNMT3A." (PMID 35580047, 2022). "Genes located in 5p that have been suggested as possible amplicon targets in sarcomas include NKD2, TERT, IRX2, TRIO, AMACR, SKP2 and RICTOR." (PMID 28652867, 2017). "Elevated SKP2 expression was observed in male instead of female patients with HNSCC, LAML, or READ (rectum adenocarcinoma); in contrast, the opposite phenomenon was found in KIRP (kidney renal papillary cell carcinoma) and SARC (sarcoma) (p < 0.05)." (PMID 37308972, 2023).
T-cell lymphoma (5 papers, 2015 to 2024). "Consistent with this latter notion, overexpression of SKP2 in mice promotes the development of prostate gland dysplasia and T cell lymphoma, whereas ablation of Skp2 impairs these processes." (PMID 32429232, 2020). "Thus, SKP2 seems to play predominantly a role of tumor promoter rather than tumor initiator in the liver, in accordance with the data obtained in the T-cell lymphoma murine model." (PMID 25537506, 2015). "Also, although overexpression of SKP2 is not sufficient to malignantly transform the T-cell compartment in the mouse, combined overexpression of SKP2 with N-Ras leads to rapid development of highly aggressive and lethal T-cell lymphomas in these animals." (PMID 25537506, 2015).
triple-negative breast carcinoma (5 papers, 2012 to 2024). An invasive breast carcinoma which is negative for expression of estrogen receptor (ER), progesterone receptor (PR), and human epidermal growth factor receptor 2 (HER2). "The mRNA level of Skp2 was also found increased in triple-negative breast cancer (TNBC) and was significantly associated with poor prognoses, and its suppression in TNBC inhibited cell proliferation and G1/S transition; evincing Skp2 as a protooncoprotein." (PMID 32165861, 2020). "More recently, multiple components of the SCFSKPCullin F box containing complex including Skp2 has been identified to be candidates of highly penetrant, synthetic lethal interactions in RB defective triple negative breast cancer." (PMID 30885218, 2019).
acute myeloid leukemia (4 papers, 2013 to 2025). Acute myeloid leukemia (AML) is a group of neoplasms arising from precursor cells committed to the myeloid cell-line differentiation. "Other studies reported that cyclin-dependent kinase 2 triggers the degradation of C/EBPα through SKP2 in acute myeloid leukemia (AML), and that SKP2 ubiquitinates C/EBPα through physically interacting with the C-terminal portion of C/EBPα in AML." (PMID 41081508, 2025).
COVID-19 (4 papers, 2021 to 2024). A disease caused by infection with severe acute respiratory syndrome coronavirus 2. "VDR activation can also inhibit S-phase kinase-associated protein 2 (Skp2), which plays a key role in the viral replication mechanism in COVID-19." (PMID 35807895, 2022). "Regarding potential VD specific actions against COVID-19, calcitriol inhibits Skp2, the protein induced by SARS-COV2 to hijack Beclin1-driven autophagy, inhibits viral replication." (PMID 34444716, 2021).
diffuse large B-cell lymphoma (4 papers, 2018 to 2024). "Specifically, SKP2 is overexpressed in diffuse large B-cell lymphoma (DLBCL) and cutaneous T-cell lymphomas (CTCLs) where it is associated with poor overall survival and abnormal cell growth, respectively." (PMID 32674429, 2020). "A similar lack of correlation between Skp2 and p27 levels has been reported in diffuse large B-cell lymphoma, suggesting that other factors may contribute to deregulation of p27 in some cancers." (PMID 30250282, 2018).
pancreatic ductal adenocarcinoma (4 papers, 2011 to 2025). An infiltrating adenocarcinoma that arises from the epithelial cells of the pancreas. "It was reported that PI3K/AKT signaling controls the binding of the transcription factor E2F1 to the Skp2 gene promoter and regulates Skp2 at the transcriptional level in pancreatic ductal adenocarcinoma cells." (PMID 29566713, 2018).
renal cell carcinoma (4 papers, 2008 to 2021). "To date, very few studies have addressed the prognostic role of P27Kip1and Skp2 in renal cell carcinoma." (PMID 18922157, 2008). "Immunohistochemistry was performed for p27Kip1, Skp2 and Cks1 in tissue microarrays of 482 renal cell carcinomas with follow-up." (PMID 18922157, 2008). "Our results suggest that immunohistochemical expression levels of p27Kip1, Skp2 and Cks1 may serve as markers with prognostic value in renal cell carcinoma." (PMID 18922157, 2008). "Furthermore, for the first time, the possible relation between levels of p27Kip1 and of its specific ubiquitin ligase subunit Skp2 and Cks1 was assessed in renal cell carcinoma." (PMID 18922157, 2008). "However, little is known regarding the prognostic utility of p27Kip1, Skp2 and Cks1 expression in renal cell carcinoma." (PMID 18922157, 2008).
skin cutaneous melanoma (4 papers, 2013 to 2023). "Recent studies have shown that Skp2 protein expression is implicated in cutaneous melanoma progression, and it may also serve as a biomarker to detect pre-malignant and malignant lesions." (PMID 23385514, 2013). "A small molecule inhibitor of Skp2, named SKPin C1, was developed and confirmed to demonstrate an inhibitory effect on cell proliferation in human skin malignant melanoma cells." (PMID 31038581, 2019).
small cell lung carcinoma (4 papers, 2015 to 2023). Small cell lung cancer (SCLC) is a highly aggressive malignant neoplasm, accounting for 10-15% of lung cancer cases, characterized byrapid growth, and early metastasis. "S-phase kinase-associated protein 2 (SKP2), a gene in which increased expression enhances the growth of small cell lung cancers, was also upregulated." (PMID 30423906, 2018). "However, considering that the number of samples with gene amplification was far smaller than that of samples with high SKP2 expression in certain cancers (e.g., small-cell lung carcinoma), it is possible that high SKP2 expression cannot be attributed solely to gene amplification." (PMID 37308972, 2023).
viral infection (4 papers, 2019 to 2022). "For instance, RNF216 or SKP2 promotes K48-ubiquitination and destabilization of Beclin 1 to inhibit autophagy in response to pathogen or viral infection." (PMID 36528652, 2022). "To explore the relevance of SKP2 inhibition on viral infection in more general terms, we also tested SKP2i in Sindbis virus (SINV) replication." (PMID 31852899, 2019). "ISG12a recruits SKP2 for ubiquitination and degradation of viral protein NS5A to restrict viral infection." (PMID 31344133, 2019).
acute lymphoblastic leukemia (3 papers, 2018 to 2024). Leukemia with an acute onset, characterized by the presence of lymphoblasts in the bone marrow and the peripheral blood. "Abnormal high Notch signaling in T-cell acute lymphoblastic leukemia (T-ALL) keeps S-phase kinase associated protein 2 (SKP2) at a high level and lowers p27Kip1, leading to more rapid cell cycle progression." (PMID 29337929, 2018). "SKP2 expression is regulated by mitogenic stimuli and by Notch signaling, a key pathway in T-cell development and in T-cell acute lymphoblastic leukemia (T-ALL); however, it is not known whether SKP2 plays a role in the development of T-ALL." (PMID 31772299, 2020).
breast invasive carcinoma (3 papers, 2012 to 2023). "For instance, decreasing SKP2 expression was also detected in older patients with BRCA (breast invasive carcinoma) and young patients with PCPG (pheochromocytoma and paraganglioma) (p < 0.05)." (PMID 37308972, 2023). "To determine the prognostic factors of invasive breast carcinomas, we applied a univariate Cox proportional hazards regression model to estimate the crude hazard ratios (HRs) of cytoplasmic Skp2 expression or clinicopathological variables on patient survival." (PMID 23300741, 2012). "In this study, we evaluate subcellular Skp2 expression in invasive breast carcinoma by immunohistochemistry to analyze the relationship between p-Akt1 and cytoplasmic Skp2 expression, and correlate the presence of cytoplasmic Skp2 with patient survival." (PMID 23300741, 2012). "Increased cytoplasmic Skp2 expression was associated with shorter DFS and OS, i.e. poorer prognosis of patients with breast invasive breast carcinoma." (PMID 23300741, 2012). "For invasive breast carcinoma patients with high cytoplasmic Skp2 and low p-Akt1 level, Skp2 inhibitors may represent a potential therapeutic strategy." (PMID 23300741, 2012). "In addition to Skp2, cytoplasmic p27 expression, menopausal status, tumor size, histological grade, and lymph node status were also significantly associated with DFS in invasive breast carcinoma." (PMID 23300741, 2012). "Results demonstrate that combined cytoplasmic Skp2 and p-Akt1 expression may be prognostic for patients with invasive breast carcinomas, and cytoplasmic Skp2 may serve as a potential therapeutic target." (PMID 23300741, 2012). "Elevated cytoplasmic Skp2 expression with low p-Akt1 expression was associated with poor disease-free and overall survival (DFS and OS), and Cox regression models demonstrated that cytoplasmic Skp2 expression was an independent prognostic marker for invasive breast carcinomas." (PMID 23300741, 2012). "We extend these results to show that a significant correlation exists between cytoplasmic Skp2 and p-Akt1 expression in patients, and suggests that increased cytoplasmic Skp2 expression may be at least partly due to Akt1 activation in invasive breast carcinomas." (PMID 23300741, 2012).